CSF1R (colony stimulating factor 1 receptor)
Diseases named in the same sentence as CSF1R in open-access papers (continued):
Sharing a sentence is not in itself a finding about the gene and the disease.
melanoma (continued). "Clinical trials testing emactuzumab, which targets colony-stimulating factor receptor 1 (CSF-1R) decreasing the M2 macrophage population, have reportedly improved prognosis of skin cancers patients, like those with melanoma." (PMID 32555170, 2020). "In pre-clinical melanoma models, treatment with CSF-1R inhibitors enhanced the efficacy of the BRAF inhibitor vemurafenib, which was associated with depleted macrophages, allowing increased anti-tumorigenic CD8+ cytotoxic T cell infiltration." (PMID 31611871, 2019). "To that end, we specifically deleted macrophages or MDSCs by injecting anti-CSF1R or anti-Ly-6G antibodies and challenged mice with B16 melanoma cells." (PMID 31554795, 2019). "In a melanoma mouse model, targeting of CSF1R on MDSCs overcomes resistance to IDO-expressing melanoma cells." (PMID 28970830, 2017). "The combination of BRAF-targeted therapy with CSF-1R blockade resulted in increased CD8 T-cell responses in the SM1 melanoma model, supporting the ongoing evaluation of this therapeutic combination in patients with BRAFV600 mutant metastatic melanoma." (PMID 25939769, 2015). "We found that MITFlow/c-JUNhigh melanomas have high levels of the myeloid cell transcripts CSF1R or CD14, arguing that in particular myeloid cell infiltrates are associated with this melanoma phenotype." (PMID 26530832, 2015). "Consistently, CD14 and CSF1R expression was higher in MITFlow/c-JUNhigh melanomas, indicating increased numbers of myeloid cells." (PMID 26530832, 2015). "We here studied the effects of CSF-1R inhibition in the context of CD8 T cell-mediated immunotherapy in the B16F10 mouse melanoma model." (PMID 25110953, 2014). "In melanoma cell lines, the pharmacological and genetic targeting of the receptor inhibited proliferation of 3D cultures and increased apoptotic rate, suggesting the pro-survival role of CSF-1R." (PMID 38254773, 2024). "In BRAF-therapy-resistant melanoma, combinatorial treatment with CSF-1R (PLX3397) and BRAF V600E (PLX4720) inhibitors at a low dose strongly increased the survival rate of murine xenograft models, as well as decreased the proliferation and invasiveness of cancer cell lines." (PMID 38254773, 2024). "Interestingly, these cancer cells did not express the transcriptional factor PU.1, a key regulator of CSF-1R expression in myeloid cells, thereby suggesting that CSF-1R expression is regulated by different transcriptional mechanisms in melanoma cells." (PMID 38254773, 2024). "Moreover, it has also been shown that the addition of CSF-1R pathway inhibition to adoptive cell therapy in preclinical melanoma models can improve the anti-tumour response." (PMID 35359423, 2022). "M2NPs selectively delivered anti-colony stimulating factor-1 receptor (anti-CSF-1R) siRNA to M2-like TAMs and eliminated 52% of M2-like TAMs, resulting in 87% reduction in melanoma tumor volume and prolonged survival, indicating that an immune memory that inhibits tumor recurrence was established." (PMID 36015212, 2022). "Second, numerous studies have demonstrated that CSF-1R also drives tumor cell progression in several cancer types, including renal cell carcinoma, ovarian cancer, colorectal cancer, bladder cancer, mesothelioma, and melanoma." (PMID 36555673, 2022). "Interestingly, DCs and TAMs are derived from the same monocyte population and can both be suppressed by anti–CSF-1R treatment to restore T cell activity in melanomas." (PMID 35380995, 2022). "Likewise, co-treatment of mice bearing BRAF V600E-driven melanoma with CSF-1R- and PD1-blocking antibodies increased efficacy when compared to single agent treatments, most likely due to the capacity of melanoma cell-derived CSF-1 to enhance TAM recruitment." (PMID 36175961, 2022). "Additionally, combining anti-CD40 mAb with CSF-1R inhibitors potently suppressed tumor growth in an autochthonous poorly immunogenic mouse melanoma model." (PMID 34771482, 2021).
melanoma (continued). "In a mouse model of melanoma, the concurrent treatment with CSF-1R inhibitor, PLX3397, and BRAF inhibitor, Vemurafenib, resulted in enhanced anti-tumor responses attributed to a significant reduction of tumor-infiltrating myeloid cells and an increase of tumor-infiltrating lymphocytes." (PMID 32656079, 2020). "For example, use of a colony-stimulating factor 1 receptor (CSF1R) inhibitor for targeting pro-tumour, tumour-associated macrophages in mouse models of LLC and melanoma resulted in the enhanced recruitment of polymorphonuclear myeloid-derived suppressor cells (PMN-MDSC)." (PMID 31289350, 2019). "Indeed, inhibition of TAMs through CSF-1R targeting led to neutrophil accumulation and enhanced metastasis formation in transplantable mouse models of melanoma, lung, colon and breast cancer." (PMID 30355585, 2018). "Furthermore, to specifically deplete macrophages and microglia, we treated AKT1-expressing larvae with the CSF-1R inhibitor Ki20227 that has previously been shown to deplete macrophages and to reduce tumor growth in a rodent melanoma model." (PMID 29465400, 2018). "Furthermore, CSF-1R inhibition enhanced the efficacy of adoptive T cell transfer in transplantable melanoma models." (PMID 30355585, 2018). "Targeting the CSF1 receptor (CSF1R) may be a new strategy in melanoma management." (PMID 35742834, 2022). "Finally, early phase studies with a PD-1 inhibitor with colony stimulating factor 1 receptor (CSFR) inhibitors have been initiated in solid tumors and melanoma (NCT02526017, NCT02452424); however, one of the trials (NCT02452424) has been terminated due to inadequate evidence of clinical efficacy." (PMID 32756436, 2020). "Furthermore, the extent of correlation of CSF1 with immune checkpoint genes was in concert with recent data implicating CSF1 as a CD8+ T-cell-dependent adaptive resistance mechanism to PD-1 blockade and showing that simultaneous CSF1R targeting may be beneficial in melanomas refractory to ICB." (PMID 37404751, 2023). "Blockage of colony-stimulating factor 1 receptor (CSF1R) signaling, involved in TAM recruitment, with pexidartinib (PLX3397), improved the efficacy of adoptive cell transfer in murine melanoma through inhibition of TAM recruitment and activation." (PMID 36010965, 2022). "In both B16 melanoma–bearing and LLC tumor–bearing mice, not only were the percentages of CD11c+ cells in the blood increased, but expression of PD-L1, CSF1R, and PDH in CD11c+ cells was also upregulated." (PMID 35917184, 2022). "Additional strategies can include the colony-stimulating factor (CSF)-1R inhibitor PLX3397 that has been shown to reduce myeloid cell infiltration and enhance adoptive cell transfer immunotherapy in BRAFV600E-driven melanoma genesis in mice." (PMID 31730502, 2019). "We used the syngeneic mouse model of BRAFV600E-driven melanoma SM1, which secretes CSF-1, to evaluate the ability of the CSF-1 receptor (CSF-1R) inhibitor PLX3397 to improve the antitumor efficacy of the oncogenic BRAF inhibitor vemurafenib." (PMID 25939769, 2015). "Inhibitors of CSF1R or its ligand CSF1 interfere with tumor-promoting TAMs or other myeloid cells in the TME and are currently being tested in clinical trials for treatment of several types of malignancies, such as CRC, melanoma or ovarian cancer." (PMID 39425000, 2025). "The inhibition of CSF1R via PLX3397 inhibitor has shown a significant effect on the tumor microenvironment, as CSF1R plays a key role in the recruitment and differentiation of monocytes into TAMs that contribute to melanoma progression." (PMID 40918451, 2025). "In addition, melanoma delivers CSF1 and IL-34 to micro-glial cells, which activates micro-glial CSF1R and thereby expands a population of trophic/phagocytic micro-glial cells that remodel the extracellular matrix and maintain a non-inflammatory phenotype." (PMID 41463339, 2025). "Notably, CSF-1R and RUNX1 inhibitors reduced the aggressiveness of tumor cells and colony size in melanoma." (PMID 38254773, 2024).
melanoma (continued). "Importantly, in the correlation analyses in human cancer patients by data mining of TCGA database, there were positive correlations among CD11C, CD274, CSF1R, and IFNG expression in lung adenocarcinoma, lung squamous carcinoma, and melanoma." (PMID 35917184, 2022). "While anti-CSF-1R treatments demonstrated limited efficacy alone, anti-CSF1R treatment in combination with anti-PD-1 therapy significantly decreased M2 TAMs while increasing the number of CD4+ and CD8+ TILs in murine models of melanoma." (PMID 35345849, 2022). "In a B16 melanoma mouse model expressing IDO, it has been shown that the blockade of colony stimulating factor 1 receptor (CSF-1R) by the kinase inhibitor PLX647 could inhibit tumor-infiltrating MDSC and enhance anti-tumor T cell responses." (PMID 29942309, 2018). "As additional murine melanoma BRAFV600E cell lines and corresponding mouse models of melanoma are developed, the effects of PLX4032 combined with other therapeutic agents such as CSF-1R inhibitors may lead to stronger synergistic antitumor responses." (PMID 25939769, 2015). "Combination therapy with the CSF-1R inhibitor PLX3397 and the oncogenic BRAF inhibitor vemurafenib result in superior antitumor effects compared to single agent treatment in a murine model of melanoma." (PMID 25939769, 2015). "Nanoparticle technology applying a CSF1R inhibitor in combination with ICI allowed for the development of a sustained codelivery method that successfully reprogramed TAMs to an antitumoral M1-like phenotype and enhanced their phagocytic capabilities in a melanoma model." (PMID 36010965, 2022). "In an autochthonous mouse melanoma model that is inherently resistant to checkpoint blockade and displays low baseline levels of CD8+ T cell infiltration, the combination of anti-CD40 and CSF-1R inhibition increased the expression of TNF-α in TAMs and IFN-γ production in T cells." (PMID 33804039, 2021). "Furthermore, one report has demonstrated that CSF1 could promote melanoma resistance to PD1 checkpoint blockade, and many reports have shown that CSF1R targeting may be beneficial by showing strong anti-tumor effects." (PMID 32582282, 2020). "Moreover, the expression of CSF-1 on tumor cells in melanoma and NSCLC patients correlated with the enrichment of MDSC that could be inhibited in vitro by the blockade of CSF-1/CSF-1R signaling." (PMID 29942309, 2018). "There were positive correlations among CD11c, PD-L1, and CSF1R expression and negative correlations with LAL expression in patients with lung cancer or melanoma using The Cancer Genome Atlas database and patient samples." (PMID 35917184, 2022). "A phase 1/1b study evaluating APX005M in combination with cabiralizumab (CSF-1R inhibitor) with or without nivolumab in NSCLC, melanoma, and RCC patients that previously have failed to respond to anti-PD-1/PD-L1 therapy (NCT03502330) is ongoing." (PMID 33804039, 2021). "A phase I trial, which enrolled 26 patients with anti-PD-1/PD-L1-resistant melanoma (n = 12), non-small cell lung cancer (n = 1) and renal cell carcinoma (n = 13), evaluated the safety of the CD40 agonist APX005M (sotigalimab) and CSF1R inhibitor (cabiralizumab) with or without nivolumab." (PMID 35742834, 2022). "CSF1R blockade with PLX647, instead, depleted suppressive MDSCs and reduced the tumor promoting activity of M2 macrophages, delaying tumor growth only in the B16-IDO melanoma model, but not in control B16." (PMID 33212945, 2020).
pancreatic cancer (62 papers, 2016 to 2025). "CTF promotes M2 polarization of tumor-associated macrophages and pancreatic cancer progression by activating the IGF2BP2-CSF1/CSF1R axis through FLG-AS1/HNRNPU-mediated histone lactylation." (PMID 41213933, 2025). "In pancreatic cancer, tumor cells expressed various CSF-1R levels, which were high in nerve-invasive PCCs, indicating that CSF-1R expression correlated with perineural migration and a worse prognosis." (PMID 38254773, 2024). "In experimental PDAC models, CSF1/CSF1R signalling in pancreatic tumours depletes CD206Hi TAMs and reprograms remaining macrophages to support anti‐tumour immunity." (PMID 38501838, 2024). "We intrasplenically implanted pancreatic cancer cells into conditional Csf1r-MerCreMer+;Grnfl/fl mice (KO) with Csf1r-MerCreMer–;Grnfl/fl (WT) as a control cohort." (PMID 38355776, 2024). "In pancreatic cancer, the combined inhibition of PI3Kγ and colony-stimulating factor-1 receptor (CSF-1R) modified the macrophage balance by decreasing M2 pro-tumor macrophages and increasing M1 anti-tumor macrophages, thus reducing the tumor volume in mice." (PMID 36765741, 2023). "In future studies, we will evaluate the crosstalk between DCs and TAMs in mouse models of pancreatic cancer and the extent to which targeting DCs resembles the efficacy of anti–CSF-1R treatment in vivo." (PMID 35380995, 2022). "CSF1R inhibitors Pexidartinib and Cabiralizumab have been tested in clinical trials with standard therapies or immune checkpoint blockade in advanced pancreatic cancer patients (NCT02777710, NCT03336216, NCT02526017)." (PMID 34290984, 2021). "CSF1R inhibitor IMC-CS4 is currently being tested in combination with pancreatic cancer vaccine and immune checkpoint blockade in pancreatic cancer patients (NCT03153410)." (PMID 34290984, 2021). "Another study showed that treatment with anti-CSF-1R resulted in the marked depletion of M2 TAMs from the TME of pancreatic carcinoma with the subsequent repolarization of the remaining TAMs to the M1 phenotype." (PMID 34205330, 2021). "In a phase 1a/b study, cabiralizumab, a monoclonal antibody targeting CSF-1R signaling, plus nivolumab four partial responses (13%) were observed in 31 patients with pancreatic cancer." (PMID 31997007, 2020). "Meanwhile, another phase I clinical trial is currently evaluating the combination of IMC-CS4 (CSF1R mAb) with pancreatic cancer vaccine (GVAX) and pembrolizumab (anti-PD-1 mAb) in patients with borderline resectable pancreatic cancer (NCT03153410)." (PMID 32664564, 2020). "The CSF-1 receptor (CSF-1R) inhibitor cabiralizumab was administered together with nivolumab in a phase I study for pretreated advanced pancreatic cancer patients." (PMID 33383713, 2020). "The CSF-1R antagonist PLX397 inhibits the infiltration of TAM into pancreatic tumors and reprograms remaining TAM to be less immunosuppressive in mice." (PMID 31138333, 2019). "Blockade of CSF-1/CSF-1R axis in a pre-clinical mouse model of pancreatic cancer metastasis impaired macrophage recruitment and induced a phenotypic switch of remaining MAMs toward a pro-inflammatory, M1-like phenotype." (PMID 31331034, 2019). "In pre-clinical pancreatic cancer models, CSF-1R signaling inhibition reduces both the numbers of tumor-infiltrating TAMs and their expression of immune-suppressive molecules and therefore acts synergistically with checkpoint inhibition." (PMID 31849950, 2019). "In pancreatic cancer, CD11b+ Ly6Gneg Ly6Clow F480+ CD206high M2-like polarized macrophages have been observed to be more sensitive to CSF-1/CSF-1R blockade." (PMID 31331034, 2019). "CSF1R was shown to be involved in the recruitment of macrophages in murine models of pancreatic cancer." (PMID 30987642, 2019). "Combination of anti- PD1 or anti- CTLA-4 checkpoint immunotherapy with CSF-1/CSF-1R blockade improved anti-tumour immunity and led to the regression of even established primary pancreatic tumours." (PMID 31331034, 2019).
pancreatic cancer (continued). "In mouse pancreatic cancer tumor transplant models, treatment with CSF1R blockade resulted in a reprogramming of the immunosuppressive tumor microenvironment." (PMID 30003190, 2018). "We next measured the expression of colony-stimulating factor-1 receptor (CSF1R) on TAMs in murine pancreatic tumors." (PMID 29719257, 2018). "find that CSF-1R+ macrophages play a vital role in pancreatic tumor maintenance, suppression of T cells, and tumor gene networks based on transcriptome analysis." (PMID 29719257, 2018). "In a mouse model of pancreatic cancer, inhibition of CSF1R signaling suppresses TAMs accumulation and their immune suppressive functions, and thereby synergize with checkpoint-blockade immunotherapy." (PMID 29387063, 2017). "In these pancreatic cancer models, combinatorial CSF1R and PD-1 or CTLA-4 blockade substantially improved responses." (PMID 28492495, 2017). "On this basis, a CSF1R inhibitor, Pexidartinib, is being combined with an anti-PD-L1 antibody, durvalumab, in a phase I study with expansion cohorts in colorectal and pancreatic cancer (NCT02777710)." (PMID 28492495, 2017). "In contrast, targeting TAM by inhibiting CSF-1R has been reported to decrease the numbers of pancreatic tumor-initiating cells and improves chemotherapeutic efficacy in vivo." (PMID 27191744, 2016). "A dose-escalation phase I study is currently underway to evaluate the safety and activity of an anti-PDL1 antibody (Durvalumab) in combination with a small-molecule CSF-1R tyrosine kinase inhibitor (Pexidartinib) in patients with metastatic/advanced pancreatic cancer or CRC." (PMID 39000110, 2024). "Moreover, SLC40A1 expression positively correlates with the expression of TAM genes (CD68, MRC1, IL10, CSF1, and CSF1R) in pancreatic tumors." (PMID 36333531, 2022). "Moreover, PI3K-γ and colony-stimulating factor-1 (CSF-1) or CSF-1 receptor (CSF-1R) pathways are also involved in the infiltration and polarization of the M2 TAMs in pancreatic cancer." (PMID 36297467, 2022). "Indeed, TAMs depletion by neutralizing CSF1R improves chemotherapeutic response through decreasing the STAT3 activation in pancreatic cancer stem cells." (PMID 35658848, 2022). "Based on this speculation, we conducted the TCGA database analysis and learned that SMS2 is positively correlated with the expression of CSF1R in pancreatic cancer." (PMID 36324684, 2022). "A recent phase 1b trial (NCT02713529) was completed that tested the safety and efficacy of AMG 820, an anti-CSF1R monoclonal antibody, in combination with anti-PD-1 antibody pembrolizumab in adults with advanced pancreatic cancer, colorectal cancer (CRC), or non-small cell lung cancer (NSCLC)." (PMID 34204306, 2021). "In addition, inhibition of colony-stimulating factor-1 receptor (CSF1R) in TAMs suppressed the metastasis of pancreatic tumors." (PMID 32986017, 2020). "Targeting TAMs by inhibiting colony-stimulating factor-1 receptor (CSF1R) or chemokine (C–C motif) receptor 2 (CCR2) decreases the number of pancreatic tumor cells and improves chemotherapeutic efficacy, inhibits metastasis and increases anti-tumoral T cell responses in vivo." (PMID 30917934, 2019). "The combination of anti-CSF-1R and anti-PD-1 antibodies promotes anti-tumor activity in pre-clinical models, and this combination is actively investigated in several clinical trials for many types of tumors, including pancreatic cancer." (PMID 30424804, 2018). "In addition, blockade of CSF-1/CSF1-R by mAb anti-CSF1 or with PLX2297 (a small molecule targeting the tyrosine kinase domain of CSF1-R) was reported to reprogram remaining TAMs at the tumor site to support antitumor immunity in pancreatic cancer mouse models." (PMID 28769933, 2017). "In addition, expression of CSF-1, the major lineage regulator for macrophages, or its receptor CSF-1R correlates with poor survival in liver and breast and pancreatic cancer, respectively." (PMID 28210073, 2017).